INS (insulin)
Diseases named in the same sentence as INS in open-access papers (continued):
Sharing a sentence is not in itself a finding about the gene and the disease.
Insulin resistance (continued). "Insulin resistance leads to mitigation of anti-lipolytic effect of insulin on adipose tissue, and lipolysis ensues with local fatty acid release triggering further local inflammation." (PMID 22035457, 2011). "Remarkably, SIRT1 activators enhance insulin sensitivity in vitro and ameliorate insulin resistance in vivo in a SIRT1-dependent manner." (PMID 20981161, 2011). "Risk factors for late progression to type 2 diabetes are similar to risk factors for early progression and include low insulin sensitivity, insulin resistance and progressive insulin secretory defect, and gain in weight and body fat." (PMID 22005617, 2011). "Insulin resistance has been shown in the vasculature of rats with Type 2 diabetes but this is, to the best of our knowledge, the first evidence for impaired insulin action in response to hyperglycemia in the retina." (PMID 22046295, 2011). "Inflammation induced by the infusion of bacterial lipopolysaccharides reduced glucose-induced insulin secretion and led to insulin resistance, and increase production of cytokines through a mechanism requiring the LPS receptor CD14." (PMID 21673955, 2011). "Consistently, PPARβ/δ overexpression helps recover insulin resistance in obesity and enhance insulin action and glucose tolerance." (PMID 20814441, 2010). "Insulin resistance, which reflects an impaired response of glucose transport to insulin, is an early characteristic in the development of type 2 diabetes." (PMID 20433743, 2010). "Insulin resistance (using any surrogate) or fasting insulin predicts ATPIII-defined MetS more accurately than IDF-defined MetS." (PMID 20374655, 2010). "And when mild stunting is associated with overweight, higher concentrations of glucose and insulin, as well as diminished function of betacells and increased insulin resistance, were found." (PMID 21318152, 2010). "Remarkably, the effect of this factor on GLUT4 is additive to the action of insulin and is fully maintained in insulin resistance." (PMID 21187969, 2010). "Insulin resistance is defined as the reduced ability of a cell to respond to physiological concentrations of insulin." (PMID 20937139, 2010). "Nevertheless, the use of definitive techniques for the measurement of insulin resistance should be considered in future studies including the euglycemic insulin clamp technique, the glucose tolerance test and the insulin suppression test." (PMID 20886095, 2010). "In vivo insulin-regulated glucose utilization was also enhanced by cinnamon extracts by increasing glucose uptake in rats with insulin resistance induced by a high-fructose diet." (PMID 20480025, 2010). "Insulin resistance, which represents a reduced physiological response of the peripheral tissues to the action of the normal levels of insulin, is amajor finding in several metabolic disorders, including type 2 diabetes and metabolic syndrome (MetS)." (PMID 20374655, 2010). "C161→T substitution at exon 6 of the PPARγ gene has been found to be associated with insulin resistance in Hispanic and non-Hispanic white women, considers to be a better predictor of fasting insulin levels and insulin resistance than P12A." (PMID 20334678, 2010). "One of the proposed mechanisms for the relation between fatty liver and insulin resistance is hepatic 'fat-overflow', which leads to lipid accumulation and then to hepatic insulin resistance followed by overall insulin resistance." (PMID 20529259, 2010). "One of the key MMPs involved in adipogenesis is MMP9, which is down-regulated by insulin and, perhaps due to insulin resistance, raised in obesity [eg.25]." (PMID 20668691, 2010). "Although the precise mechanisms for the diabetogenic effect of arsenic are still largely undefined, recent in vitro and in vivo experimental studies indicated that iAs or its metabolites impair insulin-dependent glucose uptake and result in insulin resistance." (PMID 20100676, 2010).
Insulin resistance (continued). "DAG is considered a primary inducer of insulin resistance in response to excess unsaturated fat feeding, while ceramide is synthesized directly from saturated fatty acids and antagonizes insulin action in muscle." (PMID 20706589, 2010). "In terms of obesity, metabolic syndrome, and T2DM, ghrelin is very interesting hormone, which plays a crucial role in glucose and insulin metabolism and in development of obesity and insulin resistance." (PMID 20700400, 2010). "Insulin resistance (IR) is defined as a subnormal response to both endogenous and exogenous insulin." (PMID 20507559, 2010). "In skeletal muscle, peripheral IR will primarily affect a large portion of the total glucose uptake (>80-90%), while in adipose tissue, insulin resistance will induce an impaired anti-lipolytic action of insulin and increased release of NEFA." (PMID 20426802, 2010). "In the obese men of our study, ISI values were low and insulin concentrations were increased confirming insulin resistance as a well known phenomenon in overweight subjects." (PMID 20830305, 2010). "Angiotensin II acts on insulin’s target cells and alters post-receptor mechanisms to produce insulin resistance." (PMID 20804606, 2010). "Differences in fasting insulin, insulin resistance, triglyceride, HDL-cholesterol, and C-reactive protein were slightly reduced in size, but all remained strongly statistically significant." (PMID 20421924, 2010). "On the other hand, considerable evidence is available on the effects of several polyphenols and polyphenol-rich food items in ameliorating insulin resistance and improving insulin sensitivity in experimental animals." (PMID 20480025, 2010). "As pregnancy advances insulin resistance and diabetogenic stress due to placental hormones necessitate compensatory increase in insulin secretion." (PMID 21189875, 2010). "The reasons why older persons should fail to increase their insulin secretion as much as younger persons in the face of insulin resistance are incompletely understood." (PMID 21162746, 2010). "GSK-3B has long been known as an important mediator for impaired insulin action on peripheral tissue and in the development of insulin resistance." (PMID 20942928, 2010). "Out of 113 consecutive prediabetic adults, 32 had insulin resistance (Group A) and 81 had insulin sensitivity (Group B)." (PMID 21187864, 2010). "Insulin sensitizers, such as thiazolidinediones, e.g. pioglitazone, metformin and lifestyle intervention, improve insulin resistance and thereby insulin stimulation of the adrenals and ovaries decreases." (PMID 21209881, 2010). "Improvements in glucose metabolism were evidenced by reductions in plasma glucose, plasma insulin, and insulin resistance." (PMID 21080957, 2010). "As expected, on HFD, control-mice developed significantly increased blood glucose and serum insulin concentrations suggestive of insulin resistance." (PMID 20463885, 2010). "In states of insulin resistance, shared glucotoxicity, lipotoxicity, and inflammation selectively impair PI3K-dependent insulin signaling pathways: this contributes to the reciprocal relationships between insulin resistance and endothelial dysfunction." (PMID 21203503, 2010). "Insulin resistance is defined as decreased ability of insulin to stimulate glucose disposal into the target tissue or a reduced glucose response to a given amount of insulin." (PMID 21234175, 2010). "In this context, it is likely that at the time of intraperitoneal glucose overload, the HFS group was developing a preliminary state of insulin resistance, characterized by a lower insulin sensitivity unable to compensate glucose overloads." (PMID 20534152, 2010). "This deterioration of beta cell function prevents an adequate up-regulation of insulin secretion to compensate for insulin resistance." (PMID 21162746, 2010).
Insulin resistance (continued). "One theory is that in obesity, the excess adipose tissue produces high levels of adipokines which promote insulin resistance, on the other hand, the expression of factors that promote insulin sensitivity, such as adiponectin are decreased." (PMID 20307313, 2010). "A total of 113 consecutive adults with prediabetes were enrolled for the study, 32 adults had insulin resistance (group A) and 81 had insulin sensitive (group B)." (PMID 21811521, 2010). "In according with several studies in Chinese and Japanese populations, there was weak evidence of association between rs9939609 and obesity-related metabolic traits including TC, insulin, and insulin resistance." (PMID 20858286, 2010). "The main cellular molecular mechanism of insulin desensitization, with consequent insulin resistance presents in MetS-patients, involves increased serine phosphorylation and decreased tyrosine phosphorylation of IRS-1." (PMID 20809949, 2010). "T2DM is generally characterized by hyperglycemia, insulin resistance (reduced insulin sensitivity) and obesity." (PMID 20181067, 2010). "We show that obesity induces insulin resistance, while both calorie restriction and alcohol consumption promote insulin sensitivity." (PMID 20307313, 2010). "Fasting insulin > 25 μU/ml was detected in 4 (10%) and post-load insulin level of >41 μU/ml was observed in 34 (85%) patients i.e. 85% had insulin resistance." (PMID 21234175, 2010). "The development of insulin resistance is usually an early event in the pathogenesis of type 2 diabetes and requires increased secretion of insulin to maintain euglycaemia." (PMID 20089006, 2010). "A study of 106 postmenopausal women found significant correlations between testosterone and free androgen indices versus AGEs after adjustment for age, body mass index, insulin resistance indices, and fasting glucose and insulin levels." (PMID 22254007, 2010). "Fasting insulin and glucose concentrations were used to calculate the Homeostatic Model Assessment of Insulin Resistance (HOMA) index." (PMID 20098690, 2010). "Similar to obese zucker rat, WNIN/Ob obese rats have increased peripheral insulin resistance as indicated by elevated fasting insulin, HOMA-IR and increased glucose AUC." (PMID 21083914, 2010). "Non-fasting insulin levels are determined by the ambient degree of insulin resistance together with the capacity of beta cells to compensate by insulin secretion to prevent hyperglycaemia." (PMID 21162746, 2010). "The final PCA combined measures of TG, insulin and insulin resistance with PC1 explaining 72% of the variation and PC2 explaining an additional 27%." (PMID 19403283, 2010). "μU/mL during OGTT and peak insulin above 150 μIU/mL are recommended as cut−off levels for hyperinsulinism and consequently as parameters showing insulin resistance." (PMID 21274322, 2010). "In adult humans, plasma adiponectin is an important insulin sensitizer, as its circulating level is inversely related to the body mass index and to measures of insulin resistance." (PMID 20298581, 2010). "Insulin resistance is defined as an inadequate response to the physiologic effects of circulating insulin in specific target tissues, such as skeletal muscle, liver, and adipose tissue." (PMID 20426802, 2010). "There is also a significant role for insulin and especially insulin resistance, as increasing evidence implies that the obesity-related progression of insulin resistance to T2DM parallels the progression of endothelial dysfunction to atherosclerosis." (PMID 20634940, 2010). "Inhibition of iNOS also prevented insulin resistance in myocytes exposed to cytokine/LPS while exposure of myocytes to ONOO− fully reproduced the inhibitory effect of cytokine/LPS on both insulin-stimulated glucose uptake and PI3K activity." (PMID 21206533, 2010). "Adiponectin has been shown to increase insulin sensitivity and its levels are inversely proportional to insulin resistance and type-2 diabetes." (PMID 20307313, 2010).
Insulin resistance (continued). "As a result of insulin resistance, FFAs and glucose uptake are inhibited in adipocytes, whereas increased insulin levels promote FFA flux into hepatocytes and hepatic lipogenesis." (PMID 21274430, 2010). "Results stratified by sex show significant differences between SES strata in women for fasting insulin and insulin resistance." (PMID 20394692, 2010). "OPN KO mice were protected from HFD-induced hepatic and skeletal muscle insulin resistance and had greater hepatic insulin sensitivity than WT mice when fed NC." (PMID 21103061, 2010). "The reduction of IKKβ expression partly protects mice from obesity-induced insulin resistance, and the inhibition of this kinase achieved by high doses of salicylates has been shown to improve insulin sensitivity in humans and other experimental models." (PMID 20706689, 2010). "The HOMA-IR is used for the assessment of insulin sensitivity from basal (fasting) glucose and insulin levels; a higher value indicating lower insulin sensitivity (higher insulin resistance) and vice versa." (PMID 20670429, 2010). "We show that obesity induced insulin resistance and that both calorie restriction and alcohol consumption promoted insulin sensitivity." (PMID 20307313, 2010). "For example PGC-1α overexpression results in hepatic insulin resistance, manifested by higher glucose production and diminished insulin suppression of gluconeogenesis." (PMID 20433743, 2010). "In vitro, 1,25(OH)2D induces the biosynthesis of insulin in rat pancreatic islet cells, and in another study, inhibited free fatty acid-induced insulin resistance (i.e., improved glucose uptake) in cultured myocytes in a dose-dependent manner." (PMID 20011094, 2010). "In this study, we confirmed this effect of obesity on insulin resistance and provide further evidence that CR and alcohol consumption increase insulin sensitivity." (PMID 20307313, 2010). "First, the level of reactive oxygen species (ROS) is increased under conditions of insulin resistance, while antioxidants are able to ameliorate insulin sensitivity and glucose uptake." (PMID 21187969, 2010). "Obesity induced insulin resistance and calorie restriction and alcohol improved insulin sensitivity." (PMID 20307313, 2010). "Insulin resistance is a key feature of impaired glucose tolerance in type 2-diabetes that can be characterized by a diminished ability of insulin sensitive tissues and a marked decrease of glucose metabolism in response to insulin." (PMID 20979642, 2010). "Pathogenesis of this disease involves abnormalities in glucose and lipid metabolism, including inadequate insulin secretion from pancreatic β-cells and resistance to insulin activity (insulin resistance)." (PMID 20652060, 2010). "Development of insulin resistance (stage B) was defined by elevated insulin (>3.5 ng/ml) and low random blood glucose (<150 mg/dl)." (PMID 20398338, 2010). "Recent findings suggest that FoxO1 integrates insulin signalling with hepatic mitochondrial function and inhibition of Foxo1 can improve hepatic metabolism during insulin resistance and the metabolic syndrome." (PMID 20480025, 2010). "The mice were also protected from high-fat diet-induced insulin resistance while exhibiting the same body weight, adiposity, and plasma insulin and FFA levels as wild-type controls." (PMID 20814545, 2010). "Fasting glucose and insulin concentrations, high density lipoprotein cholesterol, triglycerides, waist circumference, systolic and diastolic blood pressures were measured; insulin resistance and metabolic syndrome were also evaluated." (PMID 20529295, 2010). "Physical activity has been shown to improve skeletal muscle insulin sensitivity and reduce insulin resistance by improving glucose transport in muscle cells and improving peripheral microcirculation." (PMID 20236509, 2010). "These transcription factors modify insulin signaling and thus are involved in the development of insulin resistance." (PMID 20508722, 2010).
Insulin resistance (continued). "The contribution of POPs to insulin resistance was confirmed in cultured adipocytes where POPs, especially organochlorine pesticides, led to robust inhibition of insulin action." (PMID 20064776, 2010). "Taken together, results of these three studies demonstrate the potential of this synergistic combination of phytonutrients to favorably modulate dysregulated lipids and insulin sensitivity in insulin resistance and metabolic syndrome." (PMID 20721358, 2010). "Chronic EX treatment has been found to increase insulin sensitivity and protection against high-fat-induced insulin resistance." (PMID 20582183, 2010). "In humans, the “gold standard” for assessing insulin resistance is the euglycemic hyperinsulinemic clamp (IS clamp) because it directly measures insulin action on glucose utilization under steady-state conditions." (PMID 20622341, 2010). "With the higher dose, pregnant mice demonstrated increased insulin resistance, decreased glucose tolerance, and significantly higher fasting plasma insulin, leptin, triglyceride, and glycerol levels than F0-C mice." (PMID 20488778, 2010). "A single exercise session increases the insulin-mediated glucose utilization in normal or insulin-resistant subjects with a family history of type 2 diabetes, in obese individuals with insulin resistance and in patients with type 2 diabetes." (PMID 20946638, 2010). "In Ay mice, which develop severe insulin resistance but have robust beta-cell compensations, leucine supplementation also appears to improve insulin sensitivity." (PMID 20624298, 2010). "The state of insulin resistance leads to increased insulin secretion by pancreatic β-cells and compensatory hyperinsulinemia." (PMID 20814545, 2010). "Analysis of insulin induced phosphorylation of PKBser473 in muscle confirmed that all high fat diets induce peripheral insulin resistance." (PMID 20346174, 2010). "Insulin resistance reduces glucose uptake in skeletal muscle, whereas it hampers the normal insulin actions and enhances hydrolysis of stored TG in fat tissue." (PMID 20814441, 2010). "Offspring (F1-BPA10) also demonstrated reduced glucose tolerance, increased insulin resistance, and higher levels of plasma insulin and glycerol (an indicator of high free fatty acids)." (PMID 20488778, 2010). "Insulin resistance is defined as the decreased ability of insulin to promote glucose uptake in skeletal muscle and adipose tissue and the decreased hepatic output of glucose." (PMID 20634940, 2010). "In relation to fuel utilization, serum levels of glucose, insulin, cortisol and ketones were measured in addition calculating the homeostatic model assessment for insulin resistance (HOMA-IR)." (PMID 21092228, 2010). "By their criteria, plasma insulin levels in the upper quartile of the population defined insulin resistance." (PMID 21359028, 2010). "Insulin resistance is a measure of the biological efficiency of the endogenously produced insulin and is present when a higher than normal level of insulin is required in order to maintain normoglycemia." (PMID 21156037, 2010). "OPN is novel participant in the early pathogenesis of diet-induced insulin resistance and a modulator of insulin target tissue biology." (PMID 21103061, 2010). "Albeit 12-month-old eSS rats had an excess of fasting insulin, these animals were unable to normalize blood glucose levels indicating insulin resistance." (PMID 20236525, 2010). "Taken together, this evidence suggests that elevated FFAs in obesity activate TLR signaling and impair insulin action, providing yet another link between obesity, inflammation, and insulin resistance." (PMID 20814545, 2010). "Especilly are the serine kinases key factors in the development of insulin resistance within hepatocytes and in other insulin sensitive cells." (PMID 20426802, 2010). "In the prediabetic phase, when insulin resistance has already begun, the β-cell actually hypersecretes insulin despite normal blood glucose levels." (PMID 20700401, 2010).